ASAP1 (ArfGAP with SH3 domain, ankyrin repeat and PH domain 1)
Diseases named in the same sentence as ASAP1 in open-access papers (continued):
Sharing a sentence is not in itself a finding about the gene and the disease.
HIV-1 infection (1 paper, 2019). The type species of lentivirus and the etiologic agent of acquired immunodeficiency syndrome (AIDS). "Although its role in HIV-1 infection is unknown, overexpression of ASAP1 enhances cancer cell proliferation and invasion." (PMID 31772057, 2019).
intestinal infections (1 paper, 2026). "We reveal many novel adaptive loci with convergent signals from selection, infectious disease GWAS and immune-gene QTLs (including at FUT6 for intestinal infections; at ASAP1 for TB; and at LYZ, an antimicrobial enzyme), fine-mapping selection onto likely causal variants." (PMID 42039401, 2026).
invasive breast carcinoma (1 paper, 2023). A carcinoma that infiltrates the breast parenchyma. "This study reports that low ASAP1 expression was associated with worse recurrence-free survival in invasive breast cancer." (PMID 37762658, 2023). "Low ASAP1 protein expression was associated with worse recurrence-free survival in invasive breast cancer." (PMID 37762658, 2023). "In conclusion, the expression level of ASAP1 protein was investigated in 452 surgical specimens of primary invasive breast cancer." (PMID 37762658, 2023). "In this study, the expression level of ASAP1 protein was investigated in 452 surgical specimens of primary invasive breast cancer using immunohistochemical staining and the relationship between ASAP1 expression and patient outcomes was evaluated." (PMID 37762658, 2023). "The expression level of ASAP1 protein was measured in surgical specimens of primary invasive breast cancer cases by immunohistochemical staining." (PMID 37762658, 2023). "This study investigated the role of ASAP1 protein in invasive breast cancer." (PMID 37762658, 2023).
laryngeal carcinoma (1 paper, 2022). Carcinoma that arises from the laryngeal epithelium. "Moreover, its ectopic expression in laryngeal cancer cells was demonstrated to inhibit cell growth and invasion, and to induce cell cycle arrest and apoptosis via regulating ASAP1." (PMID 35406495, 2022).
lung carcinoma (1 paper, 2024). "In other words, staining for ASAP1 cannot discriminate invasive lung cancer cells and cells from metastatic lung lesions." (PMID 39329988, 2024). "Moreover, using ASAP1 as a sole biomarker of invasive lung cancer would be restricted due to a broad overexpression in many other malignancies (rev." (PMID 39329988, 2024).
metastatic tumors (1 paper, 2016). "This trend is exaggerated in unresectable, locally invasive or metastatic tumors, in which embryonal tumor cells are EGFR-negative, while SCU cells are EGFR-negative and ASAP1-negative." (PMID 27910913, 2016).
Mm (1 paper, 2020). "Taken together, these results showed that knockdown of Asap1 as a whole weakened zebrafish resistance to Mm infection even if they didn't obviously affect the survival status within 10 d post-infection." (PMID 33194781, 2020).
mycobacterial infection (1 paper, 2020). "Together, Our work highlights the importance of ASAP1 in modulating the balance between innate immune control and mycobacterial infection and suggests a mechanistic explanation for the reported GWAS findings between ASAP1 and TB susceptibility." (PMID 33194781, 2020). "These analyses will expand current understanding on the role of ASAP1 in anti-mycobacterial infection, and explore a preliminary mechanism for ASAP1-mediated TB susceptibility." (PMID 33194781, 2020). "Together, these findings represent a new perspective on the role of Asap1 in resistance to mycobacterial infection." (PMID 33194781, 2020).
osteosarcoma (1 paper, 2022). A usually aggressive malignant bone-forming mesenchymal neoplasm, predominantly affecting adolescents and young adults. "We individually depleted ASAP1, ASAP2, or ASAP3 in U2OS human osteosarcoma cells using SMARTpool siRNAs, replated the cells on fibronectin in serum-free media, stained the cells with fluorescent phalloidin, and examined them using laser scanning confocal microscopy." (PMID 35143843, 2022).
retinal degeneration (1 paper, 2025). Degeneration of the retina. "Additionally, expression of Arf4 mutant deficient in ASAP1-mediated GTP hydrolysis disrupted rhodopsin trafficking and caused retinal degeneration." (PMID 39774853, 2025).
Salmonella Infections (1 paper, 2020). Infections with bacteria of the genus SALMONELLA. "Genetic defects in ASAP1 mediate susceptibility to Salmonella infections, but a similar connection has not been investigated for Mycobacterium." (PMID 33194781, 2020).
serous ovarian carcinoma (1 paper, 2021). "We first demonstrate that ASAP1 is co-amplified and interacts with the focal adhesion kinase (FAK) protein in serous ovarian carcinoma." (PMID 34405025, 2021).
tauopathies (1 paper, 2024). "This suggests A1AR or ASAP1 may be promising therapeutic targets to reduce the progression of tau pathology in human tauopathies." (PMID 38472475, 2024). "Importantly, these findings indicate that A1AR and ASAP1 could serve as potential therapeutic targets for the treatment of tauopathies." (PMID 38472475, 2024).
cancer (37 papers, 2009 to 2025). A tumor composed of atypical neoplastic, often pleomorphic cells that invade other tissues. "Previous studies have reported that the ASAP1 protein is overexpressed in a variety of cancers, promoting invasion and metastasis, and is associated with poor prognosis." (PMID 37762658, 2023). "The majority of these studies also have reported that the increased expression of ASAP1 is associated with poor prognosis in various types of cancer." (PMID 37762658, 2023). "Previous studies have reported that increased expression of ASAP1 is associated with poor prognosis in various types of cancer." (PMID 37762658, 2023). "We found that the Arf-GTPase ARF6, and its downstream effector AMAP1 (also called ASAP1/DDEF1), are often overexpressed in various types of cancer, including PDAC, and closely associated with poor patient survival." (PMID 36408139, 2022). "PTK2 is located within the same genomic locus (8q24) as ASAP1, which is a region associated with aggressive cancer phenotypes, recurrence, and metastasis." (PMID 35574330, 2022). "ASAP1 emerges as a potential diagnostic marker as well as therapeutic target for cancer, as ASAP1 has been found to be implicated in multiple oncogenic processes in various cancers." (PMID 32235890, 2020). "The reduction of ASAP1 suppresses cell migration in vitro, and overexpression of ASAP1 has been associated with metastasis in cancer." (PMID 31089398, 2019). "ASAP1 is implicated in regulating survival, cell motility, and invasiveness in a number of cancers." (PMID 35143843, 2022). "Moreover, this genomic region harboured ASAP1 which encodes an oncoprotein correlated with enhancing cell motility, invasiveness, and poor survival in human cancers including HBCs60–63." (PMID 31969654, 2020). "Overexpression of ASAP1 has been associated with metastasis in cancers." (PMID 31089398, 2019). "Our findings are consistent with the previous finding that ASAP1 regulates the EMT process in cancers." (PMID 40742091, 2025). "GTPase-activating proteins (GAPs) are important regulators of small GTPases with a wide range of cellular functions; among these, ASAP1 stimulates GTP hydrolysis on Arf1 and is implicated in cancer progression." (PMID 40470248, 2025). "GTPase-activating proteins are important regulators of small GTPases; among these, ASAP1 stimulates GTP hydrolysis on Arf1 and is implicated in cancer progression." (PMID 41028713, 2025). "ASAP1 is a multidomain Arf GTPase-activating protein (ArfGAP) that catalyzes GTP hydrolysis on the small GTPase Arf1 and is implicated in cancer progression." (PMID 39763923, 2024). "Previous studies have reported that the increased expression of ASAP1 promotes invasiveness and metastasis in cancer." (PMID 37762658, 2023). "Accordingly, an oncogenic role in different cancer models was proposed for ASAP1, involved in tumour motility, invasiveness, and adhesiveness, finally leading to metastasis." (PMID 37686290, 2023). "The results showed that ASAP1 was expressed mainly in the membrane of cancer cells and partially in the cytoplasm." (PMID 36792578, 2023). "The role of the ASAP1 in promoting malignant phenotypes has been found in a variety of cancer types, and its correlation with patient prognosis suggests its potential clinical value." (PMID 36792578, 2023). "Gain in 8q chromosomal arm and especially in 8q24 region harboring amplifications in CSMD3, MYC and ASAP1 genes, has been described in different type of cancers." (PMID 36357817, 2023). "ASAP1 functions in processes ranging from cell migration, cancer cell invasion, and immune inflammation." (PMID 35143843, 2022). "Several studies have demonstrated that ASAP1 can affect integrin adhesion, actin cytoskeleton, and invasion and metastasis of cancer cells." (PMID 36309313, 2022).
cancer (continued). "A series of our studies have identified that the small GTPase ARF6 and its downstream effector AMAP1 (also called ASAP1/DDEF1) are often overexpressed in different cancers, including PDAC, and closely correlate with poor patient survival." (PMID 34001163, 2021). "ASAP1 is rarely expressed in normal tissue but is highly expressed in tumors and is well-correlated with tumor metastasis in several cancer types 24-27." (PMID 34405025, 2021). "The four genes selected through our process which are dysregulated along with CLDN1 and CLDN7 (PIK3CA, SLC6A6, ASAP1, and TMEM-43) are implicated in a variety of cancers." (PMID 34571860, 2021). "ASAP1 is involved in the regulation of cell motility and has been shown to promote cancer cell invasiveness and metastasis, thereby correlating with poor survival in CRC patients." (PMID 34571860, 2021). "In Pan Cancer Atlas, 44% of 585 patients exhibited ASAP1 upregulation or amplification and 40% of them had FAK upregulation or amplification in a subgroup of patients." (PMID 34405025, 2021). "Here, our results initially interpret that, similar to other cancer types, the aggressive BC subtype TNBC acquires driver mutations, such as amplification-dependent overexpression of MYC and ASAP1, to progress, in spite of genetic heterogeneity." (PMID 32235890, 2020). "ASAP1 has been shown to promote cell proliferation and invasion in different cancer cells, including lung, colorectal, prostate, and BC cells." (PMID 32235890, 2020). "ASAP1 is frequently amplified and overexpressed in a variety of cancers, which correlates with metastasis and poor survival." (PMID 31246957, 2019). "In other words, the main biological effects of ASAP1 favor the invasive cancer cells to migrate." (PMID 39329988, 2024). "The direct involvement of ASAP1 in the formation and functioning of subcellular structures, like CDRs and podosomes, and the reorganization of stress fibers, makes it a candidate biomarker for cancer invasiveness." (PMID 39329988, 2024). "According to the TCGA data, ASAP1 is expressed at different levels in various types of cancer." (PMID 36792578, 2023). "Similarly, in studies using cancer tissue obtained from patients, ASAP1 acted as an oncogene, and its potential as a prognostic marker was recognized." (PMID 36110251, 2022). "ASAP1 is aberrantly expressed in different cancer types including OC." (PMID 35574330, 2022). "The role of ASAP1 in cancer has been investigated in numerous studies." (PMID 36110251, 2022). "Our results suggest that targeting the upstream regulator ASAP1 and its downstream target genes may provide actionable therapeutic strategies for overcoming the intractable TNBC disease, as well as other resistant cancer types overexpressing ASAP1." (PMID 32235890, 2020). "ASAP1 has been reported to be involved in signal transduction, membrane trafficking, and cytoskeleton remodeling and promote proliferative, invasive, and metastatic phenotypes of various cancer cells." (PMID 32235890, 2020). "ASAP1 has been reported to promote invasion and metastasis in various cancer cells." (PMID 32235890, 2020). "These early results, though not reported for BC, underline the impact of ASAP1 amplification over the cancer genome." (PMID 32235890, 2020). "Together these observations suggest that ASAP1 plays a decisive role during the differentiation of mesenchymal stem cells, which may be relevant for a number of diseases such as cancer." (PMID 31246957, 2019). "Thus, the genetic alterations and mechanisms involved in AMAP1/ASAP1/DDEF1 overexpression differ among different types of cancers." (PMID 19416474, 2009). "Thus, the role of ASAP1 in cancer progression and metastasis warrants further investigation." (PMID 37762658, 2023). "The exact molecular mechanisms regulating ASAP1 in cancer are unknown." (PMID 36110251, 2022). "Furthermore, ASAP1 regulates integrin β1 recycling, and thereby promotes cancer cell invasion." (PMID 31246957, 2019).
cancer (continued). "As the PI3K/AKT pathway is one of the most commonly dysregulated pathways in cancer, future work will investigate whether ASAP1 overexpression can activate AKT signaling in cancer cells, and whether this impacts on the treatment of tumor patients with amplified or overexpressed ASAP1." (PMID 31246957, 2019). "Regulation of AKT activity by ASAP1 may be relevant for cancer progression." (PMID 31246957, 2019). "ASAP1, also known as ArfGAP with SH3, ankyrin repeat, and PH domains 1, is overexpressed in various cancers." (PMID 40742091, 2025). "We and others have previously shown that ASAP1 promotes EMT in ovarian and other cancer types 28-30." (PMID 34405025, 2021). "Our previous studies showed that ASAP1 promotes EMT in OC by activating EKR1/2 and APK pathways 29 and FAK has been shown to promote EMT in several cancer types 43-45." (PMID 34405025, 2021). "Specifically, CTTN, FAK, and ASAP1 have been demonstrated to be key regulators of tumor invasion, metastasis, and aggressive phenotypes in HNSCC and other cancers." (PMID 31731442, 2019). "We next evaluated by immunohistochemistry the expression of various SRC effectors, such as CTTN, FAK, and ASAP1, known to regulate tumor invasion, metastasis, and aggressive phenotypes in HNSCC and other cancers." (PMID 31731442, 2019). "In accordance with our recent study, DIO1 expression resulted also in suppression of TGFBI, and several other proteins (e.g. PODXL, CD74) that promote RCC progression or act as oncogenic proteins in other cancers (e.g. FMNL2, APBB1IP, ASAP1, and LRRFIP1)." (PMID 29272308, 2017). "The non-neoplastic mammary lobules adjacent to the cancer demonstrated negative to weak, heterogeneous positivity on ASAP1 staining." (PMID 37762658, 2023). "Proteins proposed for spheroid formation are ASAP1 and stabilize ISG15 in cancer cells." (PMID 35328492, 2022). "Consequently, we characterized the known oncogenes MYC and EGFR and the novel candidate genes ASAP1, IRF2BP2, and CCT5 as cancer drivers in promoting proliferation of TNBC cells." (PMID 32235890, 2020). "For instance, previously Ruk/CIN85 has been implicated in the interaction with Arf GTPase-activating protein ASAP1/AMAP1, which is one of the core components of invadopodia in invasive cancer cells, and also regulates focal adhesions, circular dorsal ruffles and membrane trafficking." (PMID 19531213, 2009). "Whether CNA-driven ASAP1 amplification and overexpression influence gene expression at a genome-wide level in cancer cells is not addressed." (PMID 32235890, 2020). "Moreover, miR-203 is a tumour suppressor identified in LSCC, and it is hypothesized to regulate ASAP1 in relation to epithelial–mesenchymal transition (EMT) and cancer stem cells." (PMID 26286725, 2015).
tumor (27 papers, 2010 to 2025). "In this study, we analyzed mice deficient in the multi-adaptor protein ASAP1, which has been implicated in tumor progression and metastasis." (PMID 31246957, 2019). "The association of FAK with ASAP1 may play a significant role in tumor metastasis and chemoresistance." (PMID 35574330, 2022). "Interestingly, both PTK2 and ASAP1 are located in an oncogenic genomic locus 8q24 and are associated with tumor metastasis and recurrence." (PMID 35574330, 2022). "Therefore, loss of EGFR expression in embryonal cells and loss of EGFR and ASAP1 expression in SCU cells may characterize the HBL tumor likely to need liver transplantation, or metastasize." (PMID 27910913, 2016). "Previous studies have shown that ASAP1 interacts with various proteins to promote tumor progression." (PMID 40742091, 2025). "ASAP1 (ArfGAP with SH3, ankyrin repeats, and PH domain 1), an ADP‐ribosylation factor GTPase‐activating protein, has been implicated in tumor metastasis." (PMID 40742091, 2025). "The results of the xenograft assay demonstrated that the SGC-7901 xenograft tumor growth was significantly reduced when ASAP1 was knocked down in SGC-7901 cells." (PMID 36792578, 2023). "The results showed that the tumor tissues from ASAP1+/− cells-injected mice were significantly reduced, compared to those from the mice injected with SGC-7901 WT cells." (PMID 36792578, 2023). "Next, we examined the influence of ASAP1 expression on the tumorigenic phenotype and tumor growth in vivo." (PMID 36792578, 2023). "Increased ASAP1 expression enhanced tumor cell invasiveness and metastasis in colorectal cancer and was associated with metastasis in prostate cancer." (PMID 37762658, 2023). "The ASAP1 knockout mice model showed significantly faster tumor growth and more frequent lung metastasis compared with the wild-type model." (PMID 37762658, 2023). "ASAP1 has also been reported to promote HCC metastasis and mediate tumor-associated macrophage infiltration in HCC." (PMID 36550445, 2022). "ASAP1 expression promotes tumor metastasis and chemoresistance by interacting with other oncogenic proteins." (PMID 34405025, 2021). "The less differentiated embryonal and SCU tumor cells also demonstrated a similar loss of immunostaining for the other EGFR pathway members, EGFR and ASAP1." (PMID 27910913, 2016). "Given the elevated expression of ASAP1 in PTC cells and its role in promoting EMT, we hypothesized that ASAP1 contributes to tumor cell growth and invasiveness." (PMID 40742091, 2025). "The expression of ASAP1 was higher in tumor tissues than in the adjacent normal tissues." (PMID 36792578, 2023). "ASAP1 promotes tumor cell progression and metastasis in vitro." (PMID 36792578, 2023). "We detected the expression of ASAP1 mRNA in 53 paired GC and tumor-adjacent normal gastric tissues." (PMID 36792578, 2023). "Additionally, the authors compared wild-type models with ASAP1 knockout models, and the ASAP1 knockout models exhibited significantly faster tumor growth, more lung metastasis, and higher invasive capacity of tumor cells." (PMID 37762658, 2023). "Therefore, the aim of this study was to elucidate the contribution of ASAP1 in the dysregulation of cytoskeletal proteins to tumor progression and chemotherapy resistance in GC cells." (PMID 36792578, 2023). "Clinical HCC samples suggested positive associations between circ-ASAP1 expression and levels of CSF-1, MAPK1, and CD68+ tumor-related-macrophages; all these could predict patient outcomes." (PMID 32665846, 2020). "In addition, low-expressed miR-203 was found in LSCC tissues, and functioned as a tumor suppressor through inhibiting proliferation, invasion and inducing apoptosis of Hep-2 cells, which was mediated by ASAP1." (PMID 29043013, 2017). "Additionally, contrary to most previous findings, this study indicates the possibility that ASAP1 may act as a tumor suppressor in specific contexts." (PMID 37762658, 2023).